SDCBP (syndecan binding protein)
Diseases named in the same sentence as SDCBP in open-access papers (continued):
Sharing a sentence is not in itself a finding about the gene and the disease.
asthma (1 paper, 2025). "The results showed that PARP1 and SDCBP had high diagnostic accuracy for asthma in the training set, with AUC values of 0.864 and 0.948, respectively." (PMID 40634444, 2025). "In GSEA, PARP1 and SDCBP were associated with immune-related processes like ‘Antigen processing and presentation’ and ‘Adaptive immune response,’ emphasizing their role in immune regulation in asthma." (PMID 40634444, 2025). "Intriguingly, the increased SDCBP expression in endobronchial biopsies tissues of asthma patients implies its potential involvement in cell survival and apoptotic resistance mechanisms." (PMID 40634444, 2025). "Specifically, future experiments will explore the mechanisms underlying anoikis in asthma, and examine how the inhibition of PARP1 and SDCBP affects anoikis and airway inflammation in asthma mouse models." (PMID 40634444, 2025). "Machine learning methods further narrowed down the six ARDEGs to two hub ARDEGs: PARP1 and SDCBP, which were significantly upregulated in asthma and validated using the GSE147878 and experimental models." (PMID 40634444, 2025). "Western blot and RT-PCR were used to further validate the expression of PARP1 and SDCBP in asthma." (PMID 40634444, 2025). "Therefore, SDCBP plays a dual role in asthma by promoting memory CD4 T cell responses while limiting activated CD8 T cell activity." (PMID 40634444, 2025). "To further verify the expression levels of PARP1 and SDCBP, we performed RT-PCR and Western blot analysis on lung tissues from OVA-induced asthma mice, compared to control mice." (PMID 40634444, 2025). "However, the role of SDCBP in asthma is mostly unknown, and no studies have explored its impact on anoikis in asthma." (PMID 40634444, 2025).
communicating hydrocephalus (1 paper, 2023). An abnormal accumulation of cerebrospinal fluid within the ventricles of the brain that occurs as a consequence of impaired cerebrospinal fluid reabsorption by the arachnoid granulations. "When the obstructive hydrocephalus group was compared to the communicating hydrocephalus group, we found one protein, syndecan binding protein (SDCBP), to differ significantly, with higher abundance in obstructive hydrocephalus." (PMID 37857909, 2023).
COVID-19 (1 paper, 2023). A disease caused by infection with severe acute respiratory syndrome coronavirus 2. "Furthermore, SDCBP has been identified as the target for the prediction and subsequent treatment of COVID-19 because this protein is involved in the positive regulation of class II HLA, which is significantly increased in patients with less severe forms of the disease." (PMID 37628421, 2023).
fibrocystic disease (1 paper, 2013). "The same pattern of SDCBP expression was identified in mammary epithelial cell lines: its expression was remarkably higher in ER-negative MDA-MB-231, Hs 578T and BT-549 BCa cells than that in ER-positive MCF-7 and T47D cells and in the fibrocystic disease epithelial cell MCF-10A." (PMID 23533663, 2013).
hepatocellular carcinoma (1 paper, 2023). A malignant tumor that arises from hepatocytes. "Moreover, SDCBP promotes macrophage migration and angiogenesis in hepatocellular carcinoma by activating NF-κB pathway." (PMID 37415981, 2023).
major depressive disorder (1 paper, 2023). An episode of depression lasting two or more weeks without an intervening episode of mania. "The common genetic characteristics of rheumatoid arthritis and major depressive disorder are EAF1, SDCBP and RNF19B." (PMID 37415981, 2023).
neuroendocrine tumors of the (1 paper, 2016). "ACTB, CDKN1B, GAPDH, GRB2, RHOA and SDCBP are potent reference genes in neuroendocrine tumors of the lung." (PMID 27802291, 2016). "In the present study, ACTB, CDKN1B, GAPDH, GRB2, RHOA and SDCBP were identified as suitable reference genes in neuroendocrine tumors of the lung." (PMID 27802291, 2016).
obstructive hydrocephalus (1 paper, 2023). An abnormal accumulation of cerebrospinal fluid within the ventricles of the brain that occurs as a consequence of an obstruction at any location within the ventricular system that prevents cerebrospinal fluid flowing into the subarachnoid space. "The proteomic profiles of patients with communicating vs. obstructive hydrocephalus were similar with only one protein, SDCBP, found to be significantly more abundant in patients with obstructive hydrocephalus." (PMID 37857909, 2023).
pancreatic cancer (1 paper, 2025). "SDCBP inhibits the CK1δ/ε-mediated phosphorylation of YAP at Ser384/Ser387 by binding to YAP1, thereby blocking β-TrCP-dependent ubiquitin-mediated degradation of YAP1 and suppressing pancreatic cancer proliferation and metastasis." (PMID 41463025, 2025).
pancreatic diseases (1 paper, 2021). "Some of them were upregulated in patients with other pancreatic diseases, such as HBB, HBA1, and KRT16 proteins, while some were upregulated only in PC groups (i.e. ALIX, GPRC5B, SDCBP, and IST1), highlighting their potential diagnostic value." (PMID 34026608, 2021). "Among the four upregulated proteins in PC group, three were interacted with each other (ALIX, SDCBP and IST1), and the fold change of ALIX expression in PC vs. other pancreatic diseases was higher compared with both SDCBP and IST1." (PMID 34026608, 2021). "Four proteins were significantly higher in PC compared with other pancreatic diseases, including PDCD6IP (also known as ALIX), GPRC5B, SDCBP, and IST1." (PMID 34026608, 2021).
pheochromocytoma (1 paper, 2021). "Therefore, in our findings, the overexpression of SDCBP might promote the metastasis of pheochromocytoma." (PMID 33828526, 2021). "In conclusion, we found that the inactivation of pVHL in pheochromocytoma led to the up-regulation of the seven novel genes, such as CTGF, SDCBP, CYR61, COL3A1, COL1A1, COL5A2, and SERPINE1." (PMID 33828526, 2021).
prostate tumors (1 paper, 2021). "The expression pattern and protein tissue localization of proteoglycans of the syndecan family (SDC 1–4) and syntenin-1 (SDCBP) were determined in normal and prostatic tumor tissue from two genetically engineered mouse models and human prostate tumors." (PMID 34445387, 2021).
cancer (55 papers, 2012 to 2026). A tumor composed of atypical neoplastic, often pleomorphic cells that invade other tissues. "In the ATGL-KO spheroids, we further identified a protein associated with invasiveness of several types of cancer: Syntenin-1 (SDCBP, O00560)." (PMID 33992777, 2021). "Aberrant expression of SDCBP in some cancers has been associated with tumor progression, metastatic dissemination, and poor prognosis via FAK, Src, p38-MAPK, AKT, NFκB, IGFBP2, EGFR, and VEGFR." (PMID 34638436, 2021). "Furthermore, the cancer-associated scaffold protein syntenin-1 (SDCBP) is known to interact with Wnts and is associated with colon CSC expansion, migration and chemoresistance; it was upregulated in HGCA tissues and non-significantly increased in the HGCA cell lines." (PMID 35842572, 2022). "SDCBP, encoded by SDCBP1, also known as syntenin-1, is a PDZ domain-containing protein highly expressed in numerous cancers, including TNBC, and correlates with poor prognosis." (PMID 40263598, 2025). "The significance of SDCBP as a target for cancer treatment was demonstrated by these investigations." (PMID 38649770, 2024). "In another study, peptides targeting SDCBP inhibited the migration and invasion of human cancer cells with high SDCBP expression by attenuating ERK phosphorylation in the MAPK pathway." (PMID 38649770, 2024). "Herein, dexrazoxane was considered for further confirmation as a drug both targeting SDCBP and possessing an anti-cancer effect." (PMID 38649770, 2024). "Elevated SDCBP expression confers a tumor-supportive role by promoting cancer cell proliferation, exaggerating the process of cell migration and invasion, and facilitating tumor angiogenesis." (PMID 38649770, 2024). "SDCBP is a widely expressed multifunctional scaffold protein mostly known for its role in cancer progression and metastasis." (PMID 37857909, 2023). "SDCBP is a multifunctional scaffold protein, which promotes the migration and invasion of cancer cells by inducing EMT." (PMID 35155233, 2022). "Related studies reported that the metastasis and spread of cancer cells were indirectly completed by many discrete processes, such as invasion, intravascular invasion, and angiogenesis, and SDCBP was a unique gene that promoted metastasis." (PMID 33828526, 2021). "Mda-9/syntenin is able to influence the cell shape and also the migration and invasion ability of different types of cancer cells, including cutaneous melanoma where high SDCBP expression has been related to metastatic spreading." (PMID 22267972, 2012). "In cancer, SDCBP reduces apoptosis and promots tumor progression and survival." (PMID 40634444, 2025). "Tumor-derived EVs were enriched in proteins associated with vesicular transport and tumorigenesis, including Laminin subunit alpha 5 (LAMA5), Syntenin-1 (SDCBP), and Tenascin (TENA), all of which are implicated in cancer progression, metastasis, and exosome biogenesis." (PMID 41149854, 2025). "SDCBP is a coding gene for syntenin-1 and is highly expressed in various types of cancer." (PMID 37298370, 2023). "SDCBP could modulate cancer cell motility and invasion through activating focal adhesion kinase (FAK), p38 MAPK, and NF-κB pathways." (PMID 35592331, 2022). "Recent studies demonstrated that SDCBP may be an important determinant of malignant phenotypes in many cancers." (PMID 28141839, 2017). "Syndecan binding protein (SDCBP) was reported involving in cancer metastatic progression." (PMID 23577100, 2013). "Syndecan Binding Protein (SDCBP) is an adapter protein possessing two tandem PDZ domains, which promote tumorigenesis and metastasis in many human cancers." (PMID 39334449, 2024). "SDCBP can increase HSP90 Kbu by binding competitively to HDAC11, with the PDZ2 domain as the functional motif, which constitutes an ideal target for cancer therapy." (PMID 37460462, 2023). "Syndecan binding protein (SDCBP) was widely distributed in intracellular proteins containing physiological and pathological role in cancers." (PMID 37508353, 2023).
cancer (continued). "Proteomic analysis, such as that of pancreatic EV samples, has identified that cancer EVs contain a distinctive protein profile, where tumor-promoting candidates such as LAMA5 (laminin subunit alpha 5), SDCBP (Syndecan Binding Protein) and TENA (Tenascin-A) were found to be overexpressed." (PMID 41226690, 2025). "Additionally, syntenin-1 (syndecan binding protein, SDCBP or MDA9), which is important for syndecan signaling, has also been involved in cancer progression." (PMID 34445387, 2021). "MDA-9/Syntenin (SDCBP) is a scaffold protein that interacts with a remarkable repertoire of key regulatory proteins, including SRC, FAK and EGFR, which are often related to expression of the tumor phenotype and cancer progression." (PMID 27472461, 2016). "SDCBP is an intracellular scaffold protein that contains the PDZ domain, and as a result can bind to a variety of proteins and participate in the regulation of biological processes such as protein transport, cancer cell metastasis, exosome secretion, and synapse formation." (PMID 37759206, 2023).
tumor (50 papers, 2012 to 2025). "Importantly, SDCBP expression was associated with Src activation, poor differentiated tumor grade, advanced tumor stage, and shorter survival rates in a series of 382 HNSCC patients." (PMID 34638436, 2021). "SDCBP expression was also associated significantly with advanced tumor stage and poor tumor grade." (PMID 34638436, 2021). "These may be because that SDCBP was positioned in the upstream of multiple tumor-associated signaling pathways." (PMID 23533663, 2013). "In detail, SDCBP overexpression caused the accumulation of BACH1 and increased expressions of BACH1-regulated pro-metastatic genes, ultimately driving tumor progression in TNBC cells." (PMID 40263598, 2025). "SDCBP plays crucial roles in regulating various processes during tumor progression, including proliferation, extracellular trafficking, immunosuppression, angiogenesis, and tumor metastasis." (PMID 40263598, 2025). "IHC staining of the 4 human ESCC specimens from which the PDX models were derived revealed high SDCBP expression in tumor#14, tumor#55 and tumor#57 and low SDCBP expression in tumor#9." (PMID 37460462, 2023). "Top 10 candidates also included proteins associated with tumor progression (LAMA5, SDCBP, TENA, PTPRJ, MUC16, TAOK1; see “Discussion”)." (PMID 35241737, 2022). "Six of 12 patients exhibited SDCBP upregulation in the tumor tissues compared to the patient-matched normal tissues, corroborating the importance of the frequent aberrant expression of SDCBP in HNSCC." (PMID 34638436, 2021). "SDCBP expression was corroborated by Western blot in paired normal and tumor tissue samples from 12 HNSCC patients." (PMID 34638436, 2021). "The current data suggests that MDA-9/syntenin (SDCBP) is part of a complex, tightly regulated connectivity network that confers self-renewal, survival and tumor progressive properties to GSCs." (PMID 27472461, 2016). "SDCBP was also reported to be responsible for cell migration, invasion and pseudopodia formation, all of which are link to tumor metastasis." (PMID 23533663, 2013). "To answer this question, we studied the tumor cell cycle changes when SDCBP was silenced in MDA-MB-231 and BT-549." (PMID 23533663, 2013). "By constructing SDCBP-silenced BCa cell clones, we further assessed the effects of SDCBP suppression on tumor cells in vitro by cell culture and in vivo by tumorigenicity." (PMID 23533663, 2013). "This study is undertaken to evaluate the expression profile of SDCBP in BCa and to explore its role in the tumor cell proliferation, and thus to assess its potential value in the targeted treatment of BCa." (PMID 23533663, 2013). "Immunohistochemical staining revealed that treatment of the 4T1 tumor with adenoviral SDCBP shRNA significantly decreased the expression levels of SDCBP, BACH1, and Ki67, but increased the expression levels of NDUFA4 and COX6B2 compared with those in the control and metformin-treated groups." (PMID 40263598, 2025). "Taken together, these results suggested that targeting SDCBP might be a novel strategy to enhance the anti-tumor efficacy of metformin when used as a therapeutic for TNBC." (PMID 40263598, 2025). "SDCBP KO resulted in a significant decrease in tumor growth compared to the control group." (PMID 40263598, 2025). "Additionally, loss of SDCBP downregulated the transcriptions of BACH1-targeted pro-metastatic genes, thereby suppressing tumor progression in TNBC cells." (PMID 40263598, 2025). "Furthermore, the role of the SDCBP‒BACH1 axis in tumor progression and metastasis, both in vitro and in vivo, was assessed." (PMID 40263598, 2025). "Syndecan binding protein (SDCBP) can promote tumor proliferation and metastasis." (PMID 39015024, 2024). "In this study, we identified dexrazoxane as an anti-tumor drug by targeting SDCBP." (PMID 38649770, 2024). "Overall, our data demonstrated that dexrazoxane may be a potential anti-tumor drug for ESCC by targeting SDCBP." (PMID 38649770, 2024).
tumor (continued). "SDCBP inhibition significantly reduced tumor growth in immunosuppressed mice." (PMID 34638436, 2021). "Immunostaining for SDCBP was present in the epithelial stroma of normal and tumor tissues." (PMID 34445387, 2021). "SDCBP shows increasing expression in tumor progression from localized to metastatic lesions." (PMID 34445387, 2021). "However, SDCBP immunostaining was moderate in tumor cells in the PIN and advanced stages of the tumor in the Pten mouse." (PMID 34445387, 2021). "MDA-9/Syntenin (SDCBP), a scaffold protein, regulates tumor pathogenesis in multiple cancers." (PMID 27472461, 2016). "The next question to ask is how SDCBP involves in the tumor cell proliferation of ER-negative BCa." (PMID 23533663, 2013). "Our results suggested that SDCBP played an important role in tumor growth of ER-negative BCas." (PMID 23533663, 2013). "The results indicated SDCBP silence inhibited ER-negative tumor cell growth in vitro." (PMID 23533663, 2013). "However, the function of SDCBP in TNBC tumor progression and in BACH1 stability remains elusive." (PMID 40263598, 2025). "Furthermore, antagomiR-216b significantly reduced tumor volume following SDCBP knockdown." (PMID 35155233, 2022). "However, a significant association between SDCBP expression and tumor TNM staging or lymph node status was not positively established (P = 0.096 and P = 0.101, respectively)." (PMID 28141839, 2017). "This study revealed a signal transduction pathway commonly found in TNBC: the interaction between SDCBP and c-src promotes the tyrosine phosphorylation of c-src at residue 419, which facilitates the transition of cells through the G1/S checkpoint to promote tumor cell proliferation." (PMID 28141839, 2017). "It was also identified that SDCBP expression was positively correlated with tumour histological grading (RS = 0.233, P = 0.003) and pTNM staging (RS = 0.163, P = 0.04); however a positive association of SDCBP expression with tumor HER-2 overexpression was not significantly established (P = 0.316)." (PMID 23533663, 2013). "Knocking down SDCBP induces BACH1 degradation and downregulates expressions of BACH1-induced metastatic genes, thereby suppressing tumor progression in mice bearing TNBC tumors." (PMID 40263598, 2025). "Our data revealed that SDCBP and BACH1 expression show a significant positive correlation in TNBC cells and TNBC patients tumor tissues." (PMID 40263598, 2025). "The downregulation of cell adhesion proteins (ITGB1, LGALS3, LGALS3BP, SDCBP, PODXL, CDCP1) further suggests a potential impact on tumor cell attachment, migration, and invasion, contributing to the anti-metastatic effects of TSA." (PMID 40429900, 2025). "Expectedly, HSPA4 overexpression increased the levels of HSPA4, HSPA5, CHOP, SDC-1, SDCBP-1, SOX4, FZD4, and β-catenin in tumor tissues, but 4-PBA inhibited the generation of these proteins." (PMID 35442158, 2022). "In the present article, we found that SDCBP is involved in CDDP resistance, representing a novel aspect of the multifaceted role of SDCBP in tumor biology." (PMID 34638436, 2021). "We found 5 potential target genes (SKP2, SMO, SDCBP, FERMT2 and PGAM1) that were consistently predicted by the three softwares and involved in tumor-related signaling pathway." (PMID 34221971, 2021). "Overall, these findings demonstrate that the oncogenic role of SDCBP in HNSCC involves the modulation of stemness, tumor aggressiveness, and metastatic potential, probably through EMT." (PMID 34638436, 2021). "For example, MES GBMs (red arrows) were enriched for CAV1, CD44, CD63, RAB27A, SDCBP and SMPDL3A, while PN (blue arrows) tumours contained higher levels of transcripts for ANXA6, CD81, hnRNPA2B1, YBX1 (RNA binding proteins) and RAB35." (PMID 30034643, 2018). "Our previous study demonstrated that SDCBP is overexpressed in TNBC, which accelerates the transition of tumor cells through the G1/S checkpoint by increasing cyclin E expression to promote the proliferation of TNBC cells." (PMID 28141839, 2017).